CCN2 (cellular communication network factor 2)
Diseases named in the same sentence as CCN2 in open-access papers (continued):
Sharing a sentence is not in itself a finding about the gene and the disease.
tumor (continued). "CCN family protein 2 (CCN2), a cysteine-rich matricellular protein, is abnormally expressed in several cancer types and involved in tumor progression or chemo-resistance." (PMID 29029514, 2017). "As compared with non-tumor liver tissues, up-regulation of CCN2 and LRP6 was observed in 68.75% (66/96) and 76.04% (73/96) HCC samples, respectively." (PMID 28870205, 2017). "Targeting of CCN2 exerts inhibitory effects on tumor development in vitro and in vivo, and more importantly, suppression of CCN2 expression remarkably improves MMC sensitivity of UBC cells." (PMID 29029514, 2017). "Higher serum CCN2 concentrations in patients with HCC are most likely due to the active fibrogenic tissue matrix surrounding the tumor and played an important role in the progression of HCC and relationship with angiogenesis of HCC." (PMID 26497214, 2016). "The fibrosis-related gene connective tissue growth factor (CTGF/CCN2) protects cells from hypoxia-mediated apoptosis, providing an in vivo selection for tumor cells that express high levels of CTGF/CCN2." (PMID 26029109, 2015). "Connective tissue growth factor (CTGF/CCN2) is a member of the CCN family of secreted proteins that are believed to play an important role in the development of neoplasia." (PMID 25738829, 2015). "Taken together, we suggest that CCN2 expression is involved in the activation of CAFs and tumor fibrous stroma formation, which is related to the aggressive biological behavior of HCC." (PMID 25126747, 2014). "Herein, we demonstrated significant CCN2 expression in HCCs with fibrous stroma (≥5% of the tumor area) (cohort 1) and even greater expression in scirrhous HCCs (fibrous stroma ≥50% of the tumor area) (cohort 2)." (PMID 25126747, 2014). "The tumour microenvironment is complex and composed of many different constituents, including matricellular proteins such as connective tissue growth factor (CCN2), and is characterized by gradients in oxygen levels." (PMID 25541962, 2014). "Whole tumor sections from representative paraffin-embedded tissue blocks were used to assess the topographic expression patterns of CCN2, EMA, K19, and FAP in scirrhous HCCs." (PMID 25126747, 2014). "Inhibition of TGF-β, which is typically activated in HCCs with fibrous stroma, was reported to downregulate CCN2 and block tumor-stroma cross-talk and tumor progression in HCC." (PMID 25126747, 2014). "CCN2 was found to be overexpressed in tumor cells from human bone metastases compared to a normal human epithelial cell line." (PMID 24551846, 2014). "Knockdown of CCN2/CTGF in TW2.6 cells was shown to reduce tumor formation and decrease E-cadherin expression in xenotransplanted tumors." (PMID 25120383, 2014). "Investigating the intracellular signalling events leading to CCN2 and type I collagen down-regulation, we found that tumour cell-mediated up-regulation of Smad7 negatively affected the MEK/ERK pathway." (PMID 24090133, 2013). "One possibility is that the tumor cells themselves express and secrete CCN2 into the circulation which then exerts its effects upon a distant organ such as the heart." (PMID 20053285, 2010). "Fairly strong CCN2 immunoreactivity was found in CgA positive (tumor) tissue obtained from both the gut and from the liver." (PMID 20053285, 2010). "Another important gene for the regulation of tumor angiogenesis, wound healing, and fibrosis is connective tissue growth factor (CCN2)." (PMID 20454645, 2010). "For example, molecular evidence has demonstrated that CCN1 and CCN2 contribute to glioma tumour progression." (PMID 18789696, 2008). "CCN1 and CCN2 expression levels also correlate positively with tumour grade and pathology and are prognostic indicators of patient survival in these tumours." (PMID 18789696, 2008). "Moreover, the expression of CCN2 correlates with high tumor grade and metastasis including bone metastasis." (PMID 40157909, 2025).
tumor (continued). "Notably, roflumilast inhibited the PDE4D/ CCN2 axis and further degraded the phosphorylation of AKT and ERK, which have been reported to be associated with metastases of numerous tumours." (PMID 39956959, 2025). "However, in tumour-derived MSCs, only CCN2 inhibited cancer cell proliferation, mobility and invasion, and it decreased the levels of MMP-9, MMP-2 and epithelial-mesenchymal transition markers in vitro." (PMID 39120301, 2024). "While in vivo follow up examining Col1a1-dependent Ccn2 loss in mice support the angiogenesis result, the impacts on tumor progression were not discussed." (PMID 38525245, 2024). "CCN2 is involved in chemoresistance to drugs in some tumor types, particularly OS." (PMID 36297616, 2022). "CCN2 is involved in numerous biological processes, including tumor progression." (PMID 36297616, 2022). "However, these analyses also revealed that the enhanced tumor initiation triggered by TIA1 downregulation was associated with an increased expression of ONCs previously identified in HepG2 cells (e.g., Spp1, Ccn2), following TIA1 silencing." (PMID 35406476, 2022). "Based on these results, the authors concluded that in OS, CCN2 increases ABCG2 expression and promotes drug resistance through the downregulation of miRNA-519d and that CCN2 inhibition might be considered as a new therapeutic option for this tumor." (PMID 34572110, 2021). "CCN2 is expressed in not only a variety of cells, including fibroblasts, endothelial cells, chondrocytes, osteoblasts, and smooth muscle cells under physiological conditions but also some inflammatory cells and tumour cells under pathological conditions." (PMID 34205668, 2021). "Altered CCN2 expression has been reported in tumor cells as well as in supporting stromal cells." (PMID 33428075, 2021). "Immunohistochemical analysis of FC1199 tumors grown in the pancreas of syngeneic C57BL/6 mice and characterized by the presence of significant amount of stroma, confirmed that CCN2 was expressed in vivo, both in tumor cells and stroma cells, but was barely detectable in healthy pancreas." (PMID 32294968, 2020). "Integrin α3β1-regulated expression of matricellular protein CCN2 during the initiation of tumorigenesis indicates that α3β1 might mediate paracrine signaling and, thus, promote the formation of a permissive tumor environment." (PMID 32423907, 2020). "We began by verifying that the tumor model expressed CCN2, the primary target of the peptides." (PMID 32294968, 2020). "Our findings that peptides based on specific amino acid sequences of CCN3 are indeed able to inhibit fibrosis and angiogenesis confirm that CCN3 can antagonize CCN2, even in a tumor setting rich in CCN2, and supports the rationale for the development of such CCN3-based compounds for PDAC therapy." (PMID 32294968, 2020). "The matricellular protein CCN2, known for mediating fibrosis in various organs including the liver, has also been shown to activate HSCs and promote tumor progression via HSC secretion of the IL-6 and STAT3 in vitro." (PMID 32850829, 2020). "The multivariate Cox proportional hazards model revealed that tumor size, number of tumor nodules, and Id-1 and CCN2 expression were also independent prognostic indicators for OS and CCR of HCC patients; however, vascular invasion was an independent prognostic indicator for OS in HCC patients." (PMID 31250351, 2019). "We detected the mRNA expression levels of Id-1 and CCN2 in 48 HCCs and their adjacent non-tumor liver tissues, and found increased Id-1 expression in 70.83% (34/48), and increased CCN2 expression in 64.58 (31/48) of HCC tissues compared with the corresponding non-tumor liver tissues." (PMID 31250351, 2019). "To evaluate CCN2 staining, we mainly focused on urothelial/tumor cells and local surrounding areas." (PMID 29029514, 2017).
tumor (continued). "Through our research, this anti-tumor effect of LMWH in this study may be contributed to the interfering core regulatory functions of CCN2 proteins that function to orchestrate the Wnt co-receptor LRP6." (PMID 28870205, 2017). "By contrast, CCN2 functions as tumor suppressors in a few circumstances." (PMID 29029514, 2017). "In the CCA tumor setting, only CCN2/CTGF and CCN4/WISP1v have been studied." (PMID 27829832, 2016). "The correlations between CCN2, K19, and fibrous stroma are of interest, in that they might imply that stemness is regulated by tumor stroma, as in various other tumors." (PMID 25126747, 2014). "Additionally, EMA expression was associated with the expression of K19, CCN2, and FAP (P<0.05 for all); EMA expressing tumor epithelial cells showed a topographic closeness to FAP-expressing CAFs." (PMID 25126747, 2014). "Moreover, the CCN2 mRNA was expressed in tumor cells of EMT-phenotype in HCC, facilitating migration, invasion, and progression of the tumor cells in vitro." (PMID 25126747, 2014). "Since fibroblasts directly co-cultured with tumour cells were found to have elevated Smad7 gene expression with downstream effects on CCN2 and type I collagen, we therefore asked whether Smad7 affects activation of the ERK signalling pathway." (PMID 24090133, 2013). "We therefore investigated whether changes in MEK/ERK signalling could account for the observed decreased CCN2 gene expression in CCD-1068SK fibroblasts co-cultured with MDA-MB-231 tumour cells." (PMID 24090133, 2013). "Interestingly, CCN2 has been identified as an oncogene in a variety of cancer types but is considered a tumor-suppressor gene in other forms of cancer." (PMID 21955589, 2011). "Under pathological conditions, such as wound healing or tumor formation it has recently been shown that Ets-1 competitively inhibits the function of another Ets factor Fli-1 to promote the expression of CCN2, thereby promoting extracellular matrix deposition during cancer." (PMID 20454645, 2010). "In addition, CCN2 expression is an independent prognostic indicator of both tumour recurrence and overall survival for intra-hepatic cholangiocarcinoma." (PMID 18789696, 2008). "Additionally, anti-CCN2 antibodies may be applicable in other diseases such as cancer; pamrevlumab was shown to inhibit pro-tumour growth cross-talk between carcinoma cells and hepatic stellate cells." (PMID 33662577, 2021). "This is in agreement with our previous observations of low CCN2 expression during late stages of tumor and spheroid growth and could further indicate that exogenous CCN2 may enhance tumorigenic potential of transformed keratinocytes predominantly during early stages of tumorigenesis." (PMID 32423907, 2020). "Moreover, CCN2/CTGF can be produced from both tumor and stromal cells." (PMID 32260433, 2020). "However, differently from our findings, CCN2 targeting with FG-3019 did not cause alterations in the tumor microenvironment, suggesting possible differences in the mechanisms of CCN2 inhibition between the antibody and the BLR peptides." (PMID 32294968, 2020). "Tumour cells may be communicating with fibroblasts in a paracrine manner by secreting soluble factors such as cytokines and growth factors that can modulate Smad7, CCN2 and type I collagen gene expression in neighbouring fibroblasts via such secreted factors." (PMID 24090133, 2013). "CST significantly suppressed CCN2, LOXL2, DDIT4, and FN1, key drivers of ECM remodeling and angiogenesis, indicating that CST disrupts the structural and metabolic axes sustaining tumor progression." (PMID 41279995, 2025). "They found that TGFβ-inducible genes, specifically CTGF (also known as CCN2) and PAI-1 (also known as SERPINE1), were among the top downregulated genes in RMS cells when exposed to tumor growth-suppressive stromal cells." (PMID 41007114, 2025).
tumor (continued). "The CCN protein family, particularly cysteine-rich protein 61 (CYR61/CCN1) and connective tissue growth factor (CTGF/CCN2), have been identified as downstream transcriptional targets of YAP and are markedly upregulated in keratinocytes within BCC tumor nests." (PMID 41550920, 2025). "mIF images visualized the spatial proximity of S100A6+ TGFBR1+ tumor cells and FAP+ CCN2+ fibroblasts." (PMID 39095854, 2024). "In the present study, we revealed a novel feedback loop between HCC tumor cells and fibroblasts mediated by the SPP1-CD44 and CCN2/TGF-β-TGFBR1 interaction pairs." (PMID 39095854, 2024). "We uncovered a positive loop between tumor cells and fibroblasts mediated by SPP1-CD44 and CCN2/TGF-β-TGFBR1 interaction pairs." (PMID 39095854, 2024). "Crucially, the inhibition of CCN2 was observed to significantly disrupt the feedback loop between tumor cells and the FAP+ fibroblasts, consequently mitigating its potential for tumor metastasis." (PMID 39095854, 2024). "Tumor oncosomal MMP3 is transferred to recipient cells and alters transcriptional programs, such as cellular communication network factor 2 (CCN2) expression, in the tumor microenvironment." (PMID 36671802, 2023). "Tumor cells that highly express CCN2 (and phosphorylate the Wnt coreceptor LRP6) have been shown to be stem cells, and heparin interacts with CCN2 to produce antitumor effects." (PMID 36297616, 2022). "Connective tissue growth factor (CTGF/CCN2) is a member of the CCN family of proteins and is involved in extracellular matrix production, desmoplasia, tumor cell proliferation, adhesion, migration, angiogenesis and metastasis." (PMID 33710604, 2021). "Increased expression of CCN1, CCN2, CCN3 and CCN4 is closely related with cell adhesion, proliferation and migration, and thus they can contribute directly to tumorigenesis, tumor development and metastases." (PMID 34940056, 2021). "The CRISPR/Cas9-mediated knockout of MMP3 showed significant anti-tumor effects such as the inhibition of migration and invasion of tumor cells, and a reduction in CCN2/CTGF promoter activity and fragmentations in vitro." (PMID 32260433, 2020). "In this study we show that BLR100 and BLR200, two CCN2-targeting, CCN3-derived peptides, can actively modify the PDAC microenvironment and increase tumor response to chemotherapy." (PMID 32294968, 2020). "The activity of the peptides has been evaluated in tumors formed by the FC1199 tumor cells, derived from KPC mice, the model used to first demonstrate the activity of the CCN2 inhibitor FG-3019 in PDAC." (PMID 32294968, 2020). "Here, we show that pharmacological inhibition of LSD1 inhibits the aggressive features of OSCC by inhibiting key target genes that function in the tumor microenvironment and EMT, including CCN2/CTGF, MMP13, LOXL4 and vimentin." (PMID 29088714, 2017). "Since CCN2 is a stretch-related ECM protein expressed in bladder detrusor, our observation was confined within the local area of urothelial/tumor cells and surrounding matrix." (PMID 29029514, 2017). "GSK-LSD1 inhibited tonsillar SCC patient-derived tumor xenografts and inhibited CCN2/CTGF, MMP13, LOXL4 and vimentin expression whereas the expression of the tumor suppressor E-cadherin increased." (PMID 29088714, 2017). "In the tumor microenvironment, MUC1 signaling has been found to reprogram transcription of connective tissue growth factor (CTGF, also called CCN2), which is a strong mediator of extracellular matrix (ECM) remodeling and angiogenesis." (PMID 28482827, 2017). "In the present study, increased expression levels of CCN2 and LRP6 were proved in oxaliplatin-resistant HCC cell lines and subcutaneous tumor tissues." (PMID 28870205, 2017). "The alterations of CCN2 and LRP6 expression levels were further validated using IHC staining in tissue microarrays (TMA) containing tumor and non-tumor tissues from 374 HCC patients (validation cohorts)." (PMID 28870205, 2017).
tumor (continued). "Previously, we found the up-regulated expression of CCN2 and LRP6 in oxaliplatin-resistant subcutaneous tumor mice screened by cDNA microarrays." (PMID 28870205, 2017). "To determine the role of CCN2 and LRP6 in HCCs, we first detected the mRNA expression levels of CCN2 and LRP6 in 96-paired HCC and adjacent non-tumor liver tissues." (PMID 28870205, 2017). "Consistent with previous reports detailing overexpression of CCN2/CTGF and CCN4/WISP1v in CCA, we detected significant overexpression of these two transcripts in all tested tumor tissues from our tumor samples." (PMID 27829832, 2016). "On the other hand, CCN2 also promoted FAK, MEK, and ERK survival signaling pathways to enhance tumor survival during cisplatin treatment." (PMID 24637722, 2014). "Interestingly, the effects of recombinant CCN2 peptide on U-CH1 cells were more pronounced under normoxia than hypoxia, promoting increased expression of CCN1, CCN2, CCN3 and CCN5, the notochord-associated markers SOX5, SOX6, T, CD24, and FOXA1 as well as increased tumour-sphere formation." (PMID 25541962, 2014). "We showed that tumour cells are able to down-regulate the expression of ECM genes such as type I collagen and CCN2, while up-regulating the expression of collagenases such as MMP1 in neighbouring fibroblasts." (PMID 24090133, 2013). "Many members of this family, such as periostin, osteopontin (SPP1), or the CNN (Cyr61, CCN2, CCN3) family of proteins, have been shown to regulate key aspects of tumor biology, including proliferation, invasion, matrix remodeling, and dissemination to pre-metastatic niches in distant organs." (PMID 37240298, 2023). "Tumor microenvironmental MMPs mediate intercellular communications via EVs that deliver MMPs into cellular nuclei to bind with HP1, leading to the gene activation of cellular communication network factor 2 (CCN2)." (PMID 36552758, 2022). "CCN2 and CCN4 were highly expressed in tumor, and CCN1, 3, 5 were increased in the normal sample." (PMID 36589241, 2022). "In this field, the most studied family member is CCN2 which also figures in Kang’s bone metastasis signature for genes cooperating in bone metastasis development irrespective of the primary tumour site." (PMID 34228239, 2021). "While HSCs respond to growth factors such as CCN2; once activated, HSCs can also modulate the ECM through secretion and upregulation of proteins such as MMPs, which are needed for HCC tumor migration." (PMID 32850829, 2020). "Thus, MMP3, CCN2/CTGF, and their EVs can be produced on both sides of the interaction to promote tumor–stroma malignant conversion." (PMID 32260433, 2020). "Connective tissue growth factor (CTGF) is the second member of the CCN family of proteins (CCN2), and CCN family proteins are involved in a number of biological processes in development, tissue repair, and tumor suppression." (PMID 32210715, 2020). "Oncosomal MMP3 also plays transcriptional roles in the induction of the cell communication network factor CCN2/CTGF, a finding which may be important for understanding a mechanism of tumor–stroma progression and metastasis." (PMID 32260433, 2020). "The in vivo subcutaneous tumor growth capacity of MHCC-97H cells transfected with CCN2 shRNA in nude mouse models was significantly diminished, whereas it is significantly enhanced when the CCN2 was rescued." (PMID 31250351, 2019). "(B) Upregulation of CCN2 and LRP6 in Oxaliplatin-treated subcutaneous tumor tissues." (PMID 28870205, 2017). "In addition, the other CCN family members including CCN1, CCN2, and CCN3 also were higher in tumor than in normal." (PMID 26824419, 2016).